DTNBP1 (dystrobrevin binding protein 1)
Diseases named in the same sentence as DTNBP1 in open-access papers (continued):
Sharing a sentence is not in itself a finding about the gene and the disease.
schizophrenia (continued). "DTNBP1 risk haplotypes for schizophrenia have been associated with decreased gene expression, whereas DTNBP1 protective haplotypes for the disorder have been associated with increased gene expression." (PMID 18945333, 2008). "In the case of the original report of allelic association between DTNBP1 gene and schizophrenia the same family sample was already known to show good evidence for linkage." (PMID 17888175, 2007). "Our data add to the growing evidence that genetic variation in the DTNBP1 gene modifies schizophrenia susceptibility by influencing general cognitive abilities." (PMID 17445278, 2007). "Recent data from two independent groups further support a role for DTNBP1 in cognition and schizophrenia susceptibility." (PMID 17445278, 2007). "Neither population displayed any significant allelic or haplotypic associations between DTNBP1 and schizophrenia." (PMID 17888175, 2007). "Elevated risk for schizophrenia is associated with a variation in the DTNBP1 gene encoding dysbindin-1, which may underpin cognitive impairments in this prevalent neuropsychiatric disorder." (PMID 39684450, 2024). "Dystrobrevin-binding protein 1 (DTNBP1) is also highly associated with schizophrenia." (PMID 38203806, 2024). "Notably, in both schizophrenia and genetic animal model of the disorder, the concomitant reduction in D3R and DTNBP1 gene expression was associated with pro-cognitive effects." (PMID 36983018, 2023). "Another electrophysiological study reported that DTNBP1 loss led to decreases in readily releasable pool in the calyx of Held synapses and could be related to the cognitive impairment in schizophrenia." (PMID 35815020, 2022). "One of the schizophrenia-susceptibility genes is the dystrobrevin-binding protein 1 (DTNBP1)." (PMID 35628556, 2022). "Genetic studies have also provided evidence of DTNBP1 impacting susceptibility to schizophrenia." (PMID 35815020, 2022). "Recently, dysbindin-1 (also termed dystrobrevin-binding protein 1), which binds to α- and β-DB in the DAPC, has been identified as a susceptibility gene for schizophrenia and polymorphisms in the dysbindin-1 gene are associated with altered emotional working memory." (PMID 36045406, 2022). "The DTNBP1 encoded Dysbindin-1 is involved in neurotransmission regulation and neurodevelopment and seems to be involved in the etiology of Schizophrenia." (PMID 35126127, 2021). "Importantly for issues to be considered further below, variations in DTNBP1 associated with schizophrenia (SNPs and haplotypes) are located in intron or promoter regions and almost all are located in the N-terminus of the gene." (PMID 32063853, 2019). "Therefore, considering the reduced dysbindin-1 expression in schizophrenic patients, together with the data from SNPs of DTNBP1 gene mutations, we propose that dysbindin-1 is an etiologic factor in schizophrenia." (PMID 28937620, 2017). "DTNBP1 gene, which encodes dysbindin-1, has been linked to schizophrenia in multiple populations." (PMID 28937620, 2017). "We investigated whether sex and genetic vulnerability (specifically, null mutation of DTNBP1 [dysbindin; a possible susceptibility gene for schizophrenia]) influence the developmental GluN2B-GluN2A switch." (PMID 27134685, 2016). "Several studies have identified DTNBP1 (or dysbindin-1) as a potential risk gene for schizophrenia." (PMID 27725886, 2016). "A study which examined potential interactions between DTNBP1 variation and serious obstetric complications in a cohort of schizophrenia patients reported that the interaction of both factors influenced risk for schizophrenia." (PMID 27725886, 2016). "Genetic variations in the human dysbindin-1 gene (DTNBP1) have been associated with schizophrenia." (PMID 27462430, 2015). "Another DTNBP1 risk haplotype (rs2619539-rs3213207-rs2619538) is also associated with reduced gray matter volumes in both the right dorsolateral prefrontal and left occipital cortex in schizophrenia." (PMID 27462430, 2015).
schizophrenia (continued). "Moreover, we have identified a single-nucleotide polymorphism (SNP) in the DTNBP1 gene that is associated with schizophrenia and results in increased expression of dysbidnin-1B mRNA." (PMID 27462430, 2015). "Notably, genetic association studies reveal that variations in the DTNBP1 are associated with prefrontal cortical functions in schizophrenia patients as well as performances in episodic and working memories in healthy subjects." (PMID 25859193, 2015). "The dysbindin-1 gene (DTNBP1: dystrobrevin binding protein 1) is a promising schizophrenia susceptibility gene, known to localize almost exclusively to neurons in the brain, and participates in the regulation of neurotransmitter release, membrane-surface receptor expression, and synaptic plasticity." (PMID 25298178, 2014). "Interestingly, the human homolog of this gene, DTNBP1, has been identified as a primary schizophrenia susceptibility gene in a variety of Genome Wide Association Studies." (PMID 24312013, 2013). "Against this background, the aims of the present study were to directly investigate the effects of at-risk single nucleotide polymorphisms of the schizophrenia/psychiatric susceptibility gene DTNBP1 on regional brain volumes in human subjects using structural MRI." (PMID 22580710, 2013). "The discrepancies between the primary and the secondary analyses may be reconciled assuming that the DAO, PPP3CC, and DTNBP1 genes modulate the susceptibility for schizophrenia only under definite circumstances." (PMID 23497497, 2013). "In particular DAO, PPP3CC, and DTNBP1, might be differentially involved in schizophrenia susceptibility according to gender and gene interaction mechanisms." (PMID 23497497, 2013). "In this context, genetic variation in DTNBP1 might confer the risk of schizophrenia or other psychiatric disorders by mediating effects on synaptic structure and function of glutamatergic neurons, particularly in the hippocampus." (PMID 22580710, 2013). "Although the results are preliminary and needed replication in a larger sample, this study suggests that NMDA receptor-mediated signalling genes (DAO, PPP3CC, DTNBP1) might be involved in schizophrenia pathogenic mechanisms related to gender." (PMID 23497497, 2013). "Thus, the question about the veritably underlying DTNBP1 schizophrenia or other psychiatric susceptibility variants still remains." (PMID 22580710, 2013). "Indeed, several DTNBP1 risk SNPs are significantly more common in the subset of schizophrenia cases marked not only by earlier adult onset and more chronic course, but by more prominent positive and negative symptoms, as well as greater cognitive deficits." (PMID 21390302, 2011). "Several SNPs of DTNBP1 have been detected and discussed as risk factors for schizophrenia." (PMID 20846375, 2010). "Recently we identified a DTNBP1 SNP (rs9370822) that is strongly associated with schizophrenia." (PMID 20615259, 2010). "Association and functional studies suggest a role for the DTNBP1 gene in schizophrenia." (PMID 20615259, 2010). "Methamphetamine psychosis is clinically similar to schizophrenia and a recent study hypothesised that DTNBP1 may also be associated with substance-induced psychoses." (PMID 20615259, 2010). "It has been supposed that particular DTNBP1 alleles increase the risk for schizophrenia and affect cognitive functions mediated by the glutamate neurotransmitter system directly affecting the development, maturation, and adult function of the prefrontal cortex." (PMID 20846375, 2010). "In addition, α-dystrobrevin binds dysbindin (also known as DTNBP1), a protein whose gene has been associated with schizophrenia and other psychiatric disorders." (PMID 19961569, 2009). "Risk genetic variations in DTNBP1, therefore, might be related to the cognitive functions affected in schizophrenia." (PMID 18945333, 2008). "The dystrobrevin-binding protein 1 (DTNBP1) gene is a susceptibility gene for schizophrenia." (PMID 17445278, 2007).
schizophrenia (continued). "Also, risk haplotypes in the DTNBP1 gene have been associated with reduced expression of DTNBP1 mRNA in brain tissue of healthy subjects and in patients with schizophrenia, whereas 'protective' haplotypes were associated with high DTNBP1 expression." (PMID 17445278, 2007). "In this study, we investigated association between single nucleotide polymorphisms (SNPs) in the DTNBP1 gene and intellectual functioning in patients with a first episode of schizophrenia or related psychotic disorder (first-episode psychosis, FEP), their healthy siblings, and unrelated controls." (PMID 17445278, 2007). "A novel DTNBP1 haplotype incorporating SNP A (T allele) has been identified in a case control sample of 708 cases and 711 controls of British and Irish descent that shows association with schizophrenia." (PMID 17888175, 2007). "Alternatively one could surmise that DTNBP1 associated schizophrenia occurs predominantly in familial cases of schizophrenia and that case control samples may therefore contain fewer cases of DTNBP1 associated schizophrenics." (PMID 17888175, 2007). "The discrepant allelic association results in previous studies of association between DTNBP1 and schizophrenia could be due population admixture." (PMID 17888175, 2007). "Previous linkage and association studies may have implicated the Dystrobrevin-binding protein 1 (DTNBP1) gene locus or a gene in linkage disequilibrium with DTNBP1 on chromosome 6p22.3 in genetic susceptibility to schizophrenia." (PMID 17888175, 2007). "Another possible mechanism by which DTNBP1 could modulate schizophrenia susceptibility, is by modulating prefrontal cortex (PFC) function." (PMID 17445278, 2007). "Therefore, we investigated association between SNPs in the DTNBP1 gene and IQ in patients with a first episode of schizophrenia or related psychotic disorder (first-episode psychosis, FEP), their unaffected siblings, and healthy controls." (PMID 17445278, 2007). "Genetic variation in the DTNBP1 gene may increase schizophrenia susceptibility by affecting intellectual functioning." (PMID 17445278, 2007). "Schizophrenia has been associated with several single nucleotide polymorphisms or haplotypes of DTNBP1 and analyses based on gene-wide association studies, coupled with other genetic and gene expression studies in humans and animals, highlighted DTNBP1 as a susceptibility gene for schizophrenia." (PMID 39684450, 2024). "We tested the hypothesis that dysbindin-1 (Dtnbp1) gene mutation combined with postnatal exposure to viral mimetic polyI:C results in schizophrenia-related behavioural changes in adulthood, and mediates polyI:C-induced inflammation in the subventricular zone (SVZ)." (PMID 30038210, 2018). "However, whether rs117610176 and decreased DTNBP1 mRNA are associated with other schizophrenia subtypes needs further investigations." (PMID 27462430, 2015). "Thus, DTNBP1 is a strong candidate for schizophrenia susceptibility gene." (PMID 27462430, 2015). "Straub and collaborators first reported an association of DTNBP1 (dystrobrevin-binding protein 1, or dysbindin) with schizophrenia in a family-based association analysis of High-Density Schizophrenia Families in Ireland (, Irish Study of High-Density Schizophrenia Families ISHDSF) in 2002." (PMID 22580710, 2013). "Other relevant findings come from the analysis of DTNBP1 gene polymorphisms and haplotypes: the observation of an influence of DTNBP1 on schizophrenia susceptibility in males could indicate the presence of sex-specific effect and/or of interactions with sex hormones." (PMID 23497497, 2013). "Genetic variants and haplotypes of DTNBP1 have frequently been reported to be associated with a number of cognitive functions, including verbal, visual, and general memory, attention, and executive function, in patients with schizophrenia and/or healthy controls." (PMID 24168225, 2013).
schizophrenia (continued). "How DTNBP1 risk SNPs or haplotypes may affect dysbindin-1 is still unknown, but it is known that levels of this protein are lower in two brain areas dysfunctional in schizophrenia." (PMID 21390302, 2011). "An increasing number of studies report that several of these DTNBP1 risk variants are associated with severity of the positive symptoms (e.g., delusions and hallucinations) and especially the negative symptoms (e.g., flattened affect and social withdrawal) of schizophrenia." (PMID 21390302, 2011). "Thus, our results suggest that executive control deficits in schizophrenia might be codetermined by DTNBP1 allele status and be based on a modification of a left prefrontal network that is already emerging in healthy risk allele carriers." (PMID 20846375, 2010). "The aim of this study was to examine whether DTNBP1 variation shows genetic association with a range of psychiatric conditions, including schizophrenia, suggesting that changes in metabolism related to variations in DTNBP1 protein function underlies a common molecular defect in these conditions." (PMID 20615259, 2010). "Since schizophrenia-related single nucleotide polymorphisms (SNPs) occur in these introns between exon 1 and exon 6, we suggest that these SNPs might affect splicing of DTNBP1, which leads to impairment of the functional interaction between dysbindin-1 and DNA-PK in schizophrenic patients." (PMID 19142223, 2009). "Since genetic variation in DTNBP1 is associated with both schizophrenia and memory function, and memory function is compromised in patients with schizophrenia, the sdy mouse may represent a useful animal model to investigate the mechanisms of memory dysfunction in the disorder." (PMID 18945333, 2008). "Given the evidence supporting DTNBP1 not only as a susceptibility gene for schizophrenia but also as a gene contributing to intellectual functioning, we hypothesized that variants in the DTNBP1 gene may contribute to the risk for schizophrenia by affecting cognitive abilities." (PMID 17445278, 2007). "Thus, genetic variation in the DTNBP1 gene may modulate schizophrenia susceptibility by altering DTNBP1 expression in areas of the brain crucial for cognitive functions." (PMID 17445278, 2007). "Dysbindin-1, a protein encoded by the schizophrenia susceptibility gene DTNBP1, is reduced in the hippocampus of schizophrenia patients." (PMID 38956130, 2024). "It has been reported that female schizophrenia patients have higher 5mC levels at the upstream CpG sites of DTNBP1." (PMID 38203806, 2024). "Further, abnormal DTNBP1 gene expression is reported within the dorsolateral prefrontal cortex (dlPFC) and hippocampus in schizophrenia, and dysbindin-1 protein expression is reported consistently as reduced within both structures." (PMID 39684450, 2024). "In this mini-review, we will discuss a potential pathogenetic mechanism for schizophrenia involving DTNBP1, BDNF, and inhibitory transmission." (PMID 35815020, 2022). "Dysbindin-1 (DTNBP1) and brain-derived neurotrophic factor (BDNF) are both genetic factors associated with schizophrenia." (PMID 35815020, 2022). "Patients with schizophrenia have significantly lower levels of DTNBP1 mRNA in the dorsolateral prefrontal cortex, hippocampus, and nucleus accumbens compared to healthy controls." (PMID 35815020, 2022). "Double knockout of DTNBP1 and COMT (catechol-O-methyl transferase, another schizophrenia risk gene) causes working memory deficits in a discrete paired-trial T-maze task, which is highly associated with dopamine function in PFC." (PMID 36590092, 2022). "Studies show that the hippocampus has high expression of DTNBP1 under normal conditions, but the levels of this protein in schizophrenia patients are significantly reduced, as supported by postmortem analysis." (PMID 35069411, 2021). "Because these prior studies focused on schizophrenia, more attention was paid to the effects of low-level DTNBP1 expression." (PMID 33679873, 2021).
schizophrenia (continued). "This study aimed to investigate the genetic effects of the schizophrenia-related gene DTNBP1 in temporal lobe epilepsy (TLE)." (PMID 33679873, 2021). "Dystrobrevin-binding protein 1 (DTNBP1), also known as dysbindin-1, has been implicated in the pathophysiology of schizophrenia." (PMID 30967545, 2019). "Downregulation of DTNBP1 expression in dorsolateral prefrontal cortex and hippocampal formation of patients with schizophrenia has been suggested to serve as a primary pathophysiological process." (PMID 32063853, 2019). "We show that the schizophrenia-relevant dysbindin-1 (Dtnbp1) gene is necessary for the innate immune response to the viral mimetic polyI:C, and that polyI:C in turn increases dysbindin-1 expression." (PMID 30038210, 2018). "Another example is the gene dystrobrevin-binding protein 1 (DTNBP1), which has been implicated in schizophrenia, bipolar disorder and major depression." (PMID 29794033, 2018). "It has been suggested that the DTNBP1 gene modulates general cognitive abilities both in schizophrenia patients and in healthy subjects in Japanese (mean age: 34.1~39.2) and German (mean age: 24.8) populations." (PMID 29209239, 2017). "Numerous studies have suggested a genetic predisposition to schizophrenia, and many genes, including DISC1, catechol-O-methyltransferase (COMT), neuregulin 1 (NRG1), and DTNBP1, have been identified as candidate susceptibility genes." (PMID 28937620, 2017). "Genetic variation in DTNBP1 affects cognitive function in patients with schizophrenia, and in the healthy population." (PMID 26171858, 2015). "Sandy mice, with spontaneous Dtnbp1 deletion, display behavioral abnormalities relevant to symptoms of schizophrenia." (PMID 25298178, 2014). "These include NOS1, AKT1, DTNBP1, DNMT1, PPP3CC and SOX10, which have previously been associated with schizophrenia." (PMID 24399042, 2014). "A recent convergent functional genomics in schizophrenia has identified top genes among which DTNBP1." (PMID 23497497, 2013). "Post-mortem brain analyses of patients with schizophrenia showed significantly reduced DTNBP1 mRNA and protein expression in the dorsolateral prefrontal cortex (DLPFC) and midbrain and in the hippocampal formation compared to healthy controls." (PMID 22580710, 2013). "DTNBP1 (dystrobrevin binding protein 1) codes for dysbindin proteins that are noted to be reduced in the hippocampi and likely frontal lobes of schizophrenia patients." (PMID 23189055, 2012). "Dysbindin-1 (dystrobrevin-binding protein 1, DTNBP1) is one of the promising schizophrenia susceptibility genes." (PMID 21448290, 2011). "Biologically, DTNBP1 is a strong candidate for schizophrenia pathogenesis as it is thought to play a pivotal role in regulating the glutamatergic system." (PMID 20615259, 2010). "Schizophrenia patients showed reduced presynaptic DTNBP1 which was related to glutamatergic alterations in intrinsic hippocampal formation connections." (PMID 20615259, 2010). "Reduced DTNBP1 mRNA and protein expression has been found in the hippocampal formation and dorsolateral prefrontal cortex of schizophrenia patients." (PMID 20615259, 2010). "It is also well known that anxiety and addictive disorders are common comorbidities of schizophrenia, so, to examine the importance of this DTNBP1 SNP in addictive and anxiety disorders, a number of psychiatric groups were genotyped for rs9370822." (PMID 20615259, 2010). "They showed that DTNBP1 is involved in the pre-synaptic protein expression and release of glutamate and that schizophrenia patients have reduced DTNBP1 mRNA levels especially in the prefrontal cortex." (PMID 20846375, 2010). "Since then, many groups have reported data that collectively support a link between schizophrenia and DTNBP1." (PMID 19142223, 2009). "This is an encouraging finding as several association and expression studies suggest that the human homolog of Dtnbp1 is one of the strongest candidates for schizophrenia." (PMID 19370154, 2009).